FADS2 (fatty acid desaturase 2)
Diseases named in the same sentence as FADS2 in open-access papers (continued):
Sharing a sentence is not in itself a finding about the gene and the disease.
type 2 diabetes (19 papers, 2012 to 2025). "The present study aims to find an association between fatty acid desaturase 2 gene polymorphism and circulating lipid levels in type-2 diabetes." (PMID 34162950, 2021). "Our results are broadly in agreement with those of previous smaller studies of the associations of FADS1 and FADS2 genetic variants or Δ-5 and Δ-6 desaturase activities with type 2 diabetes." (PMID 31690987, 2020). "This variant is located in intron 7 of the FADS2 gene and has been associated with alterations in fatty acid metabolism, inflammation, and type II diabetes." (PMID 30654845, 2019). "This study examined influence of FADS1 and FADS2 genetic variants on desaturase activities and blood lipid concentrations in type 2 diabetes patients, and further assessed their interrelationships." (PMID 28555039, 2017). "In particular, FADS2 activity has been linked to the risk of developing type 2 diabetes." (PMID 22584726, 2012). "FADS2 is an important enzyme that catalyses the metabolism of PUFAs and it plays a role in various diseases, including inflammation, cancers, type 2 diabetes and hypertension." (PMID 34095228, 2021). "Selected SNPs (FADS1: rs174547, rs174548, rs174550; FADS2: rs174575, rs174576, rs174583, rs498793 and rs2727270) were genotyped in 820 type 2 diabetes patients and compared with those reported in the HapMap." (PMID 28555039, 2017). "In this study, we genotyped SNPs (FADS1: rs174547, rs174548, rs174550; FADS2: rs174575, rs174576, rs174583, rs498793 and rs2727270) in 820 patients with type 2 diabetes and compared our findings with those reported in HapMap in a healthy population." (PMID 28555039, 2017). "There exist a research gap to explore whether genetic variations of FADS2 would exert effects on circulating lipid levels in type-2 diabetes mellitus." (PMID 34162950, 2021). "In the discovery cohort, there were 53 differentially methylated regions associated with birthweight, such as loci within Fatty Acid Desaturase 2 (FADS2) and Complexin 1 (CPLX1) genes, which in turn have been associated with type 2 diabetes and glucose-stimulated insulin release, respectively." (PMID 33212948, 2020). "This study found FADS1 rs174547 and FADS2 rs2727270 genotypes were significantly correlated with decreased D5D and D6D activities and decreased HDL-C concentrations in patients with type 2 diabetes." (PMID 28555039, 2017). "In conclusion, FADS1 rs174547 and FADS2 rs2727270 genotypes were significantly correlated with decreased HDL-C concentrations, and D5D /D6D activities as estimated as 20:4(n-6)/20:3 (n-6) and 18:3 (n-6)/18:2 (n-6) in a linear pattern in patients with type 2 diabetes." (PMID 28555039, 2017).
lung carcinoma (17 papers, 2019 to 2025). "Based on the analysis of the TCGA dataset, the expression level of the FADS2 gene demonstrated a significant association with the survival outcomes of lung cancer patients." (PMID 40535804, 2025). "Fatty acid desaturase 2 (FADS2), a key gene in the risk score model, was found to be downregulated, indicating a poor prognosis for radiotherapy patients with lung cancer." (PMID 40861806, 2025). "Analyses of clinical samples have also demonstrated elevated levels of FADS2 circular RNA in lung cancer tissues, which are associated with reduced overall survival in lung cancer patients." (PMID 40535804, 2025). "Collectively, these results suggest that FADS2 is associated with radiotherapy resistance in lung cancer." (PMID 40861806, 2025). "Of note, in some lung cancer cell lines, FADS2 activation is associated with ferroptosis suppression." (PMID 37904045, 2024). "In summary, a novel lactate-related risk score model for predicting radiotherapy outcomes has been developed, with FADS2 identified as a potent biomarker for predicting radiotherapy resistance in lung cancer." (PMID 40861806, 2025). "The lactate-related risk score, constructed using ADAMTS3, FADS2, and RTBDN, was further explored to assess their expression and prognostic value for radiotherapy patients with lung cancer across multiple databases." (PMID 40861806, 2025). "In the Human Protein Atlas database, the expression of FADS2 was lower in lung cancer tissues compared to normal lung tissues." (PMID 40861806, 2025). "The 8 FRGs (ACSL3, FADS2, GLS2, HSF1, PANX1, PHKG2, VDAC2, and CDKN1A) that we selected to be associated with the diagnosis and prognosis of lung cancer have been shown to play important roles in cancer and tumor immunity." (PMID 38743344, 2024). "FADS2 knockdown was also reported to significantly inhibit lung cancer development by increasing the levels of lipid peroxidation products and iron, which are the typical characteristics of ferroptosis." (PMID 35145965, 2022). "Microarray analysis has found that FADS2 expression is significantly upregulated compared to that in normal tissues, especially paracancerous tissues, melanoma tissues, lung cancer tissues and brain cancers." (PMID 34095228, 2021). "Knocking down FADS2 in lung cancer cells results in a significantly reduced cell growth rate, increased intracellular iron and lipid ROS levels and increased protein kinase-induced cell death." (PMID 34418989, 2021). "FADS2 has been shown to play a key role in FA desaturation in different cancer cell lines and primary tumors that are resistant to SCD inhibitors, and simultaneous blocking of both SCD and FADS2 resulted in a significant tumor reduction in hepatocellular and lung carcinoma xenografts." (PMID 40723225, 2025). "It was found that the GG allele of rs174548 was associated with reduced FADS1 expression (but not FADS2) and that omega-6 PUFAs contribute more to lung cancer risk than omega-3, with a stronger protective effect observed in women." (PMID 40430008, 2025). "Inhibiting FADS2 could reduce ferroptosis by increasing levels of Fe and lipid ROS in lung cancer cells." (PMID 35866375, 2022). "FADS2 knockdown leads to a high level of iron accumulation and lipid reactive oxygen species in lung cancer cells, indicating that FADS2 may be a suppressor factor for ferroptosis." (PMID 34095228, 2021). "Moreover, Circ-FADS2-mediated miR-498 signaling pathway contributes to lung cancer growth and viabilities, and the patients with low expression level of circFADS2 were considered to have favorable clinical outcomes." (PMID 31534962, 2019). "Furthermore, interference with FADS2 expression could protect immortalized primary hepatocytes and lung cancer cells from erastin-induced ferroptosis." (PMID 36911415, 2023).
lung carcinoma (continued). "To explore the expression and localization of FADS2 in lung cancer tissues, we analyzed single-cell RNA sequencing data from lung cancer (GSE179373) were analyzed, revealing that FADS2 was predominantly expressed in malignant cells." (PMID 40861806, 2025). "The increased methylation of ADAMTS3, FADS2 and RTBDN was found in lung cancer tissues, potentially contributing to their downregulation." (PMID 40861806, 2025). "Lung cancer, in particular, exhibits insensitivity to the inhibitory effects of SCD, favoring enhanced activity of FADS2." (PMID 40535804, 2025). "It is hypothesized that decreased FADS2 expression reduces PUFA production, leading to downregulation of OXPHOS and promoting the Warburg effect, thereby facilitating radiotherapy resistance in lung cancer." (PMID 40861806, 2025).
dyslipidemia (16 papers, 2009 to 2025). "Some studies have found significant genotype–phenotype associations between variants of FADS1/FADS2 (rs174547, rs174575) genes and atherogenic dyslipidemia (high triacylglycerol (TAG) and low high-density lipoprotein cholesterol (HDL-C) levels)." (PMID 35736500, 2022). "Among these potential candidate genes, there are six genes (CETP, APOB, TMEM258, FADS2, FADS1, and PVRL2) associated with all phenotypes of dyslipidemia." (PMID 32425817, 2020). "In conclusion, our results allowed us to define the genetic variants most associated with serum PUFA concentrations in a Mediterranean population with metabolic syndrome and to confirm the strong association between the FADS1/FADS2 locus and omega-3 PUFA (specifically DHA) in this population." (PMID 31991592, 2020). "This suggests that in individuals with the Fads2 deletion allele, the high consumption of ALA may only have an attenuated beneficial effect on the prevalence of the metabolic syndrome, which demonstrates the influence of genetic variation in Fads2 on the mediation of disease risk." (PMID 20565855, 2010). "Among these genes, four of them, SORT1, FADS1, FADS2 and GALNT2, are recently reported as candidate genes at highly replicated genetic loci contributing to polygenic dyslipidemia." (PMID 20019805, 2009). "Besides, the decline of fatty acid desaturase genes 2 (FADS2) expression was also found in women with PCOS, which was correlated with altered androgen levels and dyslipidemia." (PMID 35237237, 2022).
Hepatic steatosis (16 papers, 2017 to 2025). Steatosis is a term used to denote lipid accumulation within hepatocytes. "PUFA deficiency is known to induce hepatic steatosis (fatty liver), and previous studies showed that the ablation of FADS2 in mice exacerbates hepatic triacylglycerol and cholesterol accumulation." (PMID 37888683, 2023). "From a screen targeting 35 genes implicated in lipid metabolism and/or NAFLD risk, FADS2 (fatty acid desaturase 2) emerged as an important determinant of hepatic steatosis." (PMID 36823355, 2023). "We selected genes related to fat metabolism and fatty liver disease for these analyses, including FADS2 encoding Δ-6 desaturase and ELOVL2 encoding long chain fatty acid elongase, which are important rate-limiting enzymes in the synthesis of polyunsaturated fatty acids." (PMID 33571255, 2021). "Fatty acid desaturase 2 (FADS2) is considered a key determinant of hepatic steatosis, as its increased expression raises polyunsaturated fatty acid levels and reduces de novo lipogenesis." (PMID 41359105, 2025). "Combining organoids with CRISPR-based screening has identified FADS2 (fatty acid desaturase 2) as a critical determinant of hepatic steatosis from a 35-gene lipid metabolism dataset." (PMID 40301996, 2025). "Hendriks’ team introduces the FatTracer, a CRISPR screening platform designed to identify steatosis modulators and potential targets using APOB−/− and MTTP−/− organoids and identified fatty acid desaturase 2 (FADS2) as a key factor in hepatic steatosis." (PMID 40008122, 2025). "Histological evaluation revealed a reduction in hepatic steatosis in menhaden-fed mice compared to lard-fed mice, with flax-fed mice showing an effect that was dependent on the Fads2 genotype." (PMID 39303984, 2024). "Similarly, DNA methylation levels of the fatty acid desaturase 2 (FADS2) gene in the liver, that encodes delta‐6 desaturase, significantly affects the development of liver steatosis and its progression towards steato‐hepatitis." (PMID 40371883, 2025). "Also, we demonstrated that celastrol inhibited the transcriptional activity of PPARγ, thereby decreasing the Fabp3, Fatp1, MCAD, Fads2, and ACC1 mRNA expression in OA-induced hepatic steatosis cells." (PMID 38276299, 2024). "This supports our suggestion that altered DNA methylation in FADS2 contributes primarily to altered desaturase activity and possibly liver steatosis in NAFLD, and not to liver inflammation or fibrosis." (PMID 30654845, 2019). "Hepatic steatosis was observed in FADS2-knockout mice that were fed a diet containing C18 PUFA but no C20 PUFA, and hepatic steatosis was reduced by administering arachidonic acid." (PMID 36226194, 2022). "The transcripts of ACACA, FASN, SCD, FADS2 and FABP1 in chickens with fatty liver were significantly increased compared with those in chickens without fatty liver." (PMID 29642504, 2018).
Insulin resistance (16 papers, 2013 to 2025). Increased resistance towards insulin, that is, diminished effectiveness of insulin in reducing blood glucose levels. "In this model, insulin resistance-associated hyperinsulinemia promotes the de novo synthesis of arachidonic acid through the up-regulated expression of fatty acid elongase 2 and fatty acid desaturase 2 in the hepatocytes of the HFHSD group." (PMID 26358367, 2015). "A significant association between FADS1 and FADS2 haplotypes was found with insulin resistance while controlling for confounders." (PMID 24455201, 2013). "Together, our results suggest that a Fads2 deficiency may initially promote insulin resistance in adipose tissues, even in the context of a low-fat diet, before this is manifested in other tissues or at the whole-body level." (PMID 37085033, 2023). "In addition, the related fatty acids metabolism is also enriched in the PPAR signaling pathway or insulin resistance pathway, such as Fads2, Pparg, Acsl5, Fabp1 and Acacb." (PMID 37627267, 2023). "Many studies suggest that delta-5-desaturase (D5D) activity (FADS1) is associated with a lower risk of T2D, while stearoyl-CoA desaturase 1 (SCD1) and delta-6-desaturase (D6D, FADS2) variants are linked with insulin resistance and worsening of glucose tolerance or an increased risk of T2D." (PMID 30453550, 2018). "Thus, high BMI and insulin resistance may have increased FADS2 activity in Cluster 4, reducing the mass% of linoleic acid (C18:2 omega-6)." (PMID 36839168, 2023). "Higher expression of TCF7L2 and the fatty acid desaturases FADS1, FADS2 and SCD could contribute to insulin resistance." (PMID 26087292, 2015).
ovarian carcinoma (11 papers, 2015 to 2026). A malignant neoplasm originating from the surface ovarian epithelium. "Subsequently, a combination therapy involving cisplatin and SCD1/FADS2 inhibitors synergistically inhibited OC cell dissemination, presenting a promising chemotherapeutic strategy for managing peritoneal metastases in epithelial ovarian cancer." (PMID 40890129, 2025). "Moreover, co-treatment with SCD1/FADS2-specific inhibitors and cisplatin disrupted the metastatic spindle morphology of ovarian cancer patient-derived organoids." (PMID 37240297, 2023). "The use of inhibitors of SCD1 and FADS2 can reduce GPX4 activity and enhance the sensitivity of ovarian cancer cells to cisplatin." (PMID 39045454, 2024). "SCD1 and FASN expressions were higher and ELOVL1–6 and FADS1 expressions were lower in ovarian cancer tissue, while ACC1 and FADS2 were unchanged." (PMID 37712874, 2023). "Spheroids derived from the malignant ascites of ovarian cancer cells exhibit aberrantly elevated expression of SCD1 and fatty acid desaturase 2 (FADS2), positively accelerating lipid metabolic activities." (PMID 37240297, 2023). "Similarly, increased expression of SCD1 and fatty acid desaturase 2 (FADS2) leads to enhanced GPX4 activity, resulting in resistance to cisplatin in the ovarian cancer cell line PEO4." (PMID 39045454, 2024). "In addition, overexpression of SCD1 or FADS2 led to upregulation of the mesenchymal marker vimentin and epithelial-to-mesenchymal transition (EMT) regulators such as ZEB1, SNAIL, and Slug in ovarian cancer cells." (PMID 37240297, 2023). "Blocking SCD1/FADS2 contributed to increased cellular reactive oxygen species (ROS) and lipid peroxidation through downregulated glutathione peroxidase 4 (GPX4) and the reduced glutathione/oxidized glutathione (GSH/GSSG) ratio in ascites-derived ovarian cancer cells, thereby promoting ferroptosis." (PMID 37240297, 2023). "To determine whether fatty acid metabolism is altered in ovarian cancer tissue, we first evaluated the gene expression of fatty acid synthases (ACC1, FASN), fatty acid desaturases (SCD1, FADS1, FADS2) and fatty acid elongase 1–6 (ELOVL1–6) in ovarian tumor tissues and normal ovarian tissues." (PMID 37712874, 2023). "Thus far, this is an innovative report about the inhibition of FAM that could trigger FINs-induced ferroptosis in ovarian cancer, at least in part, by modulating SCD1/FADS2." (PMID 36499591, 2022).
melanoma (10 papers, 2012 to 2025). A malignant, usually aggressive tumor composed of atypical, neoplastic melanocytes. "Human melanoma cells stably expressing control shRNA or FADS2 shRNA were intravenously injected, and the amount of lung metastases was compared." (PMID 37849907, 2021). "To further evaluate the importance of FADS2-mediated fatty acid desaturation in melanoma metastasis, we tested the impact of FADS2 inhibition on cell migration." (PMID 37849907, 2021). "Mice injected with melanoma cells containing FADS2 knockdown developed fewer lung metastases compared to the mice injected with control melanoma cells." (PMID 37849907, 2021). "Together, these results indicate that FADS2 is a potential therapeutic target for suppressing melanoma metastasis." (PMID 37849907, 2021). "At the same time, a recent report revealed that FADS2-mediated sapienate metabolism is regulated by the mTOR-SREBP1/2 axis, providing another possibility for the regulatory mechanism of FADS2 in melanoma." (PMID 37849907, 2021). "It is likely that high FADS2 activity in MITFlow/AXLhigh melanoma cells converted the palmitate into sapienate, thus increasing the membrane fluidity." (PMID 37849907, 2021). "Importantly, sapienate supplementation rescued the migration capacity of the cells with either FADS2 inhibition methods, indicating that sapienate has a functional role in promoting melanoma cell migration." (PMID 37849907, 2021). "Importantly, as the high migration and invasion capacities presented in the melanoma can be suppressed by FADS2 inhibition in vitro and in vivo, inhibition of FADS2-mediated fatty acid desaturation offers a therapeutic opportunity to treat metastatic melanoma." (PMID 37849907, 2021). "Importantly, our TCGA database analysis indicates that while SCD is expressed at similar levels, FADS2 expression is significantly upregulated in metastatic melanoma compared to primary melanoma." (PMID 37849907, 2021). "Therefore, one potential mechanism of increased dependency on FADS2-mediated fatty acid desaturation in MITFlow/AXLhigh LD-rich melanoma cell lines could be a compensatory mechanism due to reduced MITF-regulated SCD." (PMID 37849907, 2021). "Consequently, inhibition of FADS2 suppresses melanoma migration in vitro and metastasis in vivo." (PMID 37849907, 2021). "Upregulation of additional genes from the bile acid and peroxisome signaling pathways was also evident in TIL gene and pathway expression analysis, including upregulation of SOD1, ACSL5, FADS2, CAT, DHCR24, SLC27A2, and IDH2 in melanoma TILs compared to pCD8s." (PMID 38023136, 2023). "To validate the presence of unsaturated fatty acids in LDs, we treated LD-rich melanoma cells with desaturase inhibitors, CAY10566 and SC26196, for inhibiting Stearoyl-CoA desaturase-1 (SCD) and FADS2, respectively." (PMID 37849907, 2021). "In particular, the unsaturated fatty acid, sapienate, synthesized through fatty acid desaturase 2 (FADS2), is found to play an essential role in promoting melanoma migration, which may be mediated through membrane fluidity regulation." (PMID 37849907, 2021). "When the other fatty acid desaturase, SCD1, was inhibited, the migration capacity of MITFlow/AXLhigh melanoma cells was not significantly changed, suggesting that FADS2 is a specific target for suppressing melanoma metastasis." (PMID 37849907, 2021).